HOXA10 (homeobox A10)
Diseases named in the same sentence as HOXA10 in open-access papers (continued):
Sharing a sentence is not in itself a finding about the gene and the disease.
tumor (73 papers, 2008 to 2026). "HOXA10 encodes one of the DNA-binding transcription factors that regulate gene expression, morphogenesis and differentiation, functioning as a tumor suppressor gene." (PMID 27993161, 2016). "Finally, in vivo tumor xenograft experiments were performed with nude mice to elucidate the effects associated with HOXA10-mediated HDAC1 regulation of DNMT1/KLF4 on the tumorigenic ability of LAD." (PMID 33596966, 2021). "SGI-110, a new DNA methytransferace inhibitor, was found to reduce stem cell property of OC in a low dose through inducing re-expression of differentiation-associated genes HOXA10, therefore decreasing tumor initiating capacity and re-sensitizing CSCs to platinum." (PMID 27304054, 2016). "In vitro silencing of HOXA10 increased cancer cell viability and invasion, therefore suggesting that HOXA10 functions as a tumor suppressor gene in GC." (PMID 39858044, 2025). "Clinically, HOXA10 elevation is associated with increased EMT scores, tumor advancement and PCa recurrence." (PMID 38932472, 2024). "In a subcutaneous xenograft model, RFX6 overexpression profoundly enhanced tumor growth, but this effect was significantly reduced with HOXA10 knockdown." (PMID 38932472, 2024). "We further evaluated the impact of HOXA10 on RFX6‐driven PCa tumor progression using luciferase‐labeled 22Rv1 cells in SCID mice." (PMID 38932472, 2024). "HOXA1, HOXA2, HOXA3, and HOXA10 had high expression in GBM tumor tissues compared to normal tissues." (PMID 37351805, 2023). "miR-204-5p is an additional well-documented tumor suppressor, which affects PCa growth by controlling the expression of the Homeobox A10 (HOXA10) and Meis Homeobox 1 (MEIS1), as well as the anti-apoptotic gene BCL2." (PMID 36608541, 2023). "HOXA10 gene can inhibit tumor cell proliferation, reduce invasion ability, and inhibit tumor cell metastasis." (PMID 37033258, 2023). "In recent years, researches concerning the relation between HOXA10 and tumor progression have been gradually increasing." (PMID 33563300, 2021). "The results showed that HOXA10 was significantly upregulated in the GC tumor samples than the adjacent normal mucosae (mean IS = 3.98 vs. 1.50, P < 0.001)." (PMID 33563300, 2021). "In contrast, p-eIF2α was predicted to negatively regulate tumor suppressors like the homeobox protein HOXA10, estrogen-related receptor alpha (ESRRA), polycomb group protein ASXL1, and mitofusin 2 (MFN2) function 43–46." (PMID 34330898, 2021). "After silencing HOXA10, the results revealed that tumor growth was slowed while tumor weight was markedly diminished, while tumor growth was accelerated and the weight significantly elevated following HDAC1 overexpression." (PMID 33596966, 2021). "Of the top 20 down-regulated genes, miR-646 host gene and homeobox A10 (HOXA10) are of great relevance given their emerging tumor suppressive functions." (PMID 32344635, 2020). "HOXA10 overexpression promoted GC cell proliferation, enhanced tumor growth, and inhibited apoptosis." (PMID 31364281, 2019). "A series of in vitro and in vivo experiments indicated that overexpression of HOXA10 in GC cells accelerated cell proliferation and tumor growth with reduced apoptosis." (PMID 31364281, 2019). "Upregulated HOXA10 promoted GC cell proliferation with reduced apoptosis in vitro and accelerated GC tumor growth in vivo." (PMID 31364281, 2019). "In this study, we have combined tumor histological explorations, transcriptomic studies in cell lines, and functional investigations to characterize HOXA10 expression and function in TGCT tumorigenesis." (PMID 30581773, 2018).
tumor (continued). "HOXA10 serves as a good marker for prognosis of various tumors, and its high expression leads to enhanced tumor propagation." (PMID 30545354, 2018). "Hoxa10 knockdown substantially inhibited tumor growth, increased cytotoxic CD8+ T cell infiltration, reduced tumor-infiltrating barrier (TIB) density at tumor margins, and decreased immunosuppressive macrophage populations while enhancing macrophage-CD8+ T cell interactions." (PMID 41736051, 2026). "Therefore, HOXA10 has potential as a novel prognostic biomarker for increased survival in patients with intestinal mucin phenotype GC through possible action as a tumor suppressor gene." (PMID 39858044, 2025). "HOXA10, a transcription factor, plays an important role in tumor progression." (PMID 40498062, 2025). "To further understand the role of HOXA10 in PCa, we explored its effects on tumor cell phenotypes." (PMID 38932472, 2024). "In addition to their association with AML prognosis, CPNE8, HOXA10, and SPINT2 were also found to be prognostically relevant across multiple tumor types." (PMID 39555062, 2024). "The local tumor microenvironment as well as transcription factor HOXA10 could stimulate the expression of ALKBH5 in tumor cells 27,28." (PMID 36632222, 2023). "Moreover, in GC tumor samples, HOXA10 was negatively correlated with E-cadherin (r = − 0.469, P < 0.001)." (PMID 33563300, 2021). "Tumor weight and volume were reduced by lentivirus-mediated elevation of miR-195 by inhibition of HOXA10, which could be annulled by LINC00461 overexpression." (PMID 33869744, 2021). "Furthermore, we analyzed the expression correlation between HOXA10 and E-cadherin in 127 paired GC tumor samples and found that HOXA10 was inversely correlated with E-cadherin (r = − 0.469, P < 0.001)." (PMID 33563300, 2021). "In addition, the expression levels of HOXA10 in the tumor tissues of nude mice treated with miR-195-5p agomir were lower than those in the agomir NC tumors." (PMID 34925694, 2021). "Moreover, in the presence of miR-195, the lentivirus-mediated silencing of HOXA10 by shRNA further reduced the tumor weight and volume and slowed the overall growth rate." (PMID 33869744, 2021). "The xenograft model demonstrated that HOXA10 promoted tumor growth and resistance to cisplatin." (PMID 34496932, 2021). "HOXA10 is reported as either an oncogene or a tumor suppressor, depending on the cancer types." (PMID 32841292, 2020). "Meanwhile, the expression of LINC00461, miR‐195 and HOXA10 was assessed in the respective tumours." (PMID 31967713, 2020). "Therefore, it is possible that the in vitro expression of HoxA10, HoxA11, and HoxB13 differs from that of tumor tissues in vivo." (PMID 31137902, 2019). "Altogether, these findings demonstrated that HOXA10 enhanced GC cells tumor growth in vivo." (PMID 31364281, 2019). "In breast cancer, miR-135a promotes tumor migration and invasion by targeting HOXA10." (PMID 27486383, 2016). "Therefore, HOXA10 regulated tumor growth in a cancer-specific manner." (PMID 34925694, 2021). "Therefore, HOXA10 may regulate the tumor biological behaviors and radiosensitivity of the LUAD cells through the Wnt/β-catenin pathway." (PMID 34925694, 2021).
tumor (continued). "However, the differences of cytoplasm expression of HOXA10 between tumor cells and cell lines may reflect their different in vivo and in vitro growth conditions." (PMID 30581773, 2018). "Collectively, these findings confirm that HOXA10 mimics the effects of RFX6 on orchestrating aggressive PCa cellular behavior in vitro and tumor growth in vivo." (PMID 38932472, 2024). "Homeobox A10 (HOXA10) belongs to the HOX gene family, which plays an essential role in embryonic development and tumor progression." (PMID 33563300, 2021). "have exemplified that HOXA10, targeted by miR-135a-5p, is overexpressed in HNSCC cells, and the inhibition of its expression can inhibit tumor growth in vivo and cell proliferation in vitro." (PMID 33869744, 2021). "HOXA10-induced upregulation of HDAC1 interacts with DNMT1-KLF4 axis, while the inhibition of HOXA10 or HDAC1 represents a promising anti-tumor therapy target for LAD." (PMID 33596966, 2021). "HOXA7, HOXA10 and HOXA13, which are highly expressed in LSCC tissues, have a weak positive correlation with tumor purity." (PMID 33763449, 2020). "Downregulation of HoxA10, HoxA11, and HoxB13 in KPA cells is unexpected, because these Hox genes act as tumor-promoting genes in several types of cancers." (PMID 31137902, 2019). "Marker genes differentially expressed in the blastemal tumours relative to triphasic tumours included CM (EYA1, HOXA10, NR2F2) and PA (WT1) genes." (PMID 29040332, 2017). "Notable exceptions were genes such as SPP1, HOXA10 and MMP14, for which the greatest differential increase in expression was at the comparative interface between thin and I.M. thickness tumor samples." (PMID 18442402, 2008). "More importantly, we found HOXA10 had higher expression in GC tumor samples with LNM than those of non-LNM (mean IS = 4.45 vs. 3.19, P < 0.001)." (PMID 33563300, 2021). "HOXA10, as a member of homeobox (HOX) genes, promotes tumor progression in multiple cancers." (PMID 34294084, 2021). "Similarly, HOXA10, LEFTY1, and MT1H have all been suggested to act as tumor suppressors, whose overexpression leads to a better prognosis." (PMID 32841292, 2020). "To provide evidence for the possible ceRNA regulatory mechanism of HOTTIP, we performed a pilot study on the HOTTIP-miRNA-mRNA network by detecting the expression pattern of HOTTIP-miR195-5p-HOXA10 in HNSCC cell lines and tumor samples in comparison to normal cell lines and normal tissues." (PMID 31032351, 2019). "These processes occur at the nuclear level, and thus, the inhibition of HOXA10 does not affect the tumor suppressor function of PTEN that occurs in the cytoplasm." (PMID 25061500, 2014). "The 5-year survival rate in patients with HOXA10 positive tumours was only 30%, but it was 55.6% in the HOXA10 negative group." (PMID 21906307, 2011). "HOXA10 expression also occurred more frequently in GC tissues that expressed caudal type homeobox 2 (CDX2), in which this gene plays an important role in the regulation of intestinal epithelial cells and has been recognized as a possible GC tumor suppressor gene." (PMID 39858044, 2025). "Conditional ablation of either SHP-2 or PD-1 in myeloid cells resulted in augmented phosphorylation of HOXA10 and IRF8 in vitro and enhanced differentiation, activation, phagocytosis and inflammatory responses in myeloid cells of tumor-bearing mice, leading to diminished tumor growth." (PMID 36581713, 2023). "Results showed that HOTTIP along with HOXA10 was upregulated in HNSCC cell lines and tumor samples, while miR195 was downregulated in HNSCC cell lines and tumor samples, which indicated that HOTTIP might increase HOXA10 expression through downregulating miR195." (PMID 31032351, 2019). "In these types of cancers, miR-494 functions its tumor suppressive effects, and inhibites cell proliferation, cell migration, and cell invasion and promoting apoptosis by regulating different oncogenes in different cancer cells, such as VEGF, CXCR4, CLPTM1L, HOXA10, and c-MYC." (PMID 26317788, 2015).
tumor (continued). "Among the 17 upregulated genes, we selected the top five, i.e. CDX1, SI, KRT16, HOXA10, and SERPINB5 for validation using RT-PCR in the 20 pairs of tumor and non-tumor tissues that were not used in RNA-seq." (PMID 28418924, 2017). "They found that high HOXA10 expression was predictive of resistance of treatment, including TMZ treatment, independent of the MGMT methylation status of the tumor." (PMID 25061500, 2014). "When expressed ectopically in an undifferentiated ovarian mouse tumour, HOXA7 was shown to promote the ability of HOXA9, HOXA10 and HOXA11 to induce Müllerian differentiation rather than induce lineage specificity itself." (PMID 21906307, 2011).
cancer (62 papers, 2012 to 2026). A tumor composed of atypical neoplastic, often pleomorphic cells that invade other tissues. "HOXA10 has been implicated in the deregulation of multiple cancer types via activation of the JAK1/STAT3 signaling pathway." (PMID 40612864, 2025). "We found that chromatin interactions, genetic alterations, and gene regulation were associated with cancer heterogeneity and subtypes in TC, and indicated the enrichment of CoMut with Gli2, HOXA10, and HIF2α around TADs in TC." (PMID 36609218, 2023). "Multiple enriched genes (Hoxa6, Hoxa10, and Meis1) in the pathway of transcriptional misregulation in cancer were associated with LSC self-renewal and survival." (PMID 36593968, 2023). "The methylation of the HOXA9 and HOXA10 promoters is associated with cancer progression in various cancers." (PMID 28748001, 2017). "HOXA10 plays an important role in regulating cell differentiation, maturation, development and proliferation, and has been implicated in the occurrence and development of certain cancers." (PMID 33596966, 2021). "Immune checkpoint blockade (ICB) treatment was administered to investigate the role of HOXA10 in cancer immunotherapy." (PMID 41736051, 2026). "Given the parallels between implantation and other physiological or pathological processes involving regulated EMT, such as wound healing, fibrosis, and cancer metastasis, our work highlights HOXA10 as a potential node in broader E/M regulatory networks." (PMID 41213962, 2025). "Of these, key cancer-associated genes shown to be upregulated by the SySa fusion were downregulated by TAK-981 treatment, including CDX2, HOXA10, SUZ12, TYMS, AURKB, and HOXC10 and SMC2." (PMID 40804185, 2025). "Homeobox A10 (HOXA10) is a transcription factor associated with apoptosis and cell proliferation in many types of cancers." (PMID 40792071, 2025). "Accumulating evidence has reported that HOXA10 serves as a carcinogenesis in the progression of various human cancers." (PMID 36407869, 2022). "Our analysis herein identified six additional functionally associated HOXA9 proteins, (including HOXA10) which are predicted to interact with HOXA9 and are classified as having a role in transcriptional regulation in cancer." (PMID 35743243, 2022). "HDAC1 mediated the effects of HOXA10 on cancer cell proliferation, migration, invasion, cell cycle progression, and apoptosis." (PMID 33596966, 2021). "Intriguingly, the function of the HOXA10 gene is quite comprehensive, and acts as both a proliferation enhancer and proliferation inhibitor in cancers." (PMID 31013831, 2019). "More evidence needs to be explored to determine which cancer types are suitable for therapeutic interference of cell proliferation with HOXA10 and other HOX proteins." (PMID 31013831, 2019). "Collectively, these context-specific roles of HOXA10 in cancer cell proliferation serve as a cautionary reminder of therapeutic targeting of HOXA10." (PMID 31013831, 2019). "Using these programs, we selected HOXA10 as a miR-139-5p target gene for further study, as HOXA10 was important for malignant behavior in other types of cancer." (PMID 29618950, 2018). "The analysis for KEGG pathway indicated the involvement of HOXA9 and HOXA10 in the “Transcriptional misregulation in cancer”, playing a possible role in cell differentiation resistance." (PMID 29101335, 2017). "A significant increase in the number of γ-H2AX foci was demonstrated in iHOXA10-treated cells, indicating that inhibition of HOXA10 impairs the HR DNA repair system, potentially keeping cancer cells from escaping death after anticancer treatment." (PMID 25061500, 2014). "The HOXA10 gene is a regulator of embryonic morphogenesis and differentiation and is aberrantly expressed in several types of cancers." (PMID 22439757, 2012). "Among these, HOXB7, HOXA13, HOXA10, and HOXC10 have been associated with cancer." (PMID 38761291, 2024).